INS (insulin)
Diseases named in the same sentence as INS in open-access papers (continued):
Sharing a sentence is not in itself a finding about the gene and the disease.
type 1 diabetes (continued). "Approximately 5–10% of diabetics with type 1 diabetes (T1D) show gradual destruction of the insulin producing β-cells in the pancreas." (PMID 25574400, 2014). "Most patients with long-duration type 1 diabetes continue to secrete very low levels of endogenous insulin, which increase after meals." (PMID 24121625, 2014). "A strong inverse association between the incidence of severe hypoglycemia and hemoglobin A1c (HbA1c) levels has been described in previous decades in adults and children with type 1 diabetes using intensive insulin therapy." (PMID 25289645, 2014). "Diabetes is caused when this system breaks down: either the body attacks its own β-cells (type I diabetes), or the body stops responding properly to insulin (type II)." (PMID 24714494, 2014). "It is a reliable, sensitive and specific method for assessment of insulin secretion in type 1 diabetes, with test material remaining stable for 3 days at room temperature, allowing outpatients to easily be tested." (PMID 24121625, 2014). "Islet transplantation is a promising therapy for severely insulin-dependent diabetes patients in whom the endogenous insulin secretion is insufficient." (PMID 24743240, 2014). "Further, none of these studies were conducted in a patient population of newly diagnosed children with type 1 diabetes, when the choice of basal insulin is initially made." (PMID 24653838, 2014). "GB rapidly decreased BMI, HbA1c, and insulin requirements in severely obese women with type 1 diabetes." (PMID 24668543, 2014). "Although exogenous insulin therapy through the insulin pump or subcutaneous insulin injection temporally delays the onset of complications, it finally results in type I diabetes mellitus." (PMID 24959189, 2014). "This case confirms that insulin-induced localized involutional lipoatrophy in type-1 diabetes can occur again, and can be cured by systemic corticosteroids." (PMID 24961832, 2014). "Studies have indicated that bone marrow mesenchymal stem cells (BMSCs) and embryonic stem cells (ESCs) can differentiate into insulin-producing cells and can used in transplantion therapy for type 1 diabetes." (PMID 24297321, 2014). "Type I diabetes is usually treated with insulin injections, but there is increasing interest in the possibility of replacing the defective β-cells instead." (PMID 24714494, 2014). "Low-level insulin secretion can be detected by measuring urinary C-peptide in patients with long-duration type 1 diabetes." (PMID 24121625, 2014). "Increased frequencies of MMc were observed in type 1 diabetes pancreas (p = 0.03) with particular enrichment in the insulin positive fraction (p = 0.01)." (PMID 24498006, 2014). "Currently, insulin injection treatment and pancreatic islet cell transplantation are the only effective treatments for type I diabetes." (PMID 25526563, 2014). "We have characterized the changes of adipose cell size repartition and gene expressions in type 1 diabetes Sprague-Dawley rats and type 1 diabetic supplemented with insulin." (PMID 25170835, 2014). "We report a recurrence of insulin-induced localized involutional lipoatrophy at the abdominal wall in a 57-year-old Caucasian woman with type-1 diabetes on continuous subcutaneous insulin infusion." (PMID 24961832, 2014). "This suggests that tight hyperglycemic control, in a model of autoimmune diabetes that mimics human type 1 diabetes, contributes in part to the renoprotective actions of the insulin by preventing the deleterious effect of high glycemic load." (PMID 24400109, 2014). "This study demonstrates that GB rapidly and significantly reduces BMI, HbA1c, and insulin requirements in severely obese women with type 1 diabetes." (PMID 24668543, 2014). "This study was unique in that it examined the question of the influence of the choice of basal insulin, along with other factors, on glycemic control in the first year of diagnosis with type 1 diabetes." (PMID 24653838, 2014).
type 1 diabetes (continued). "The estrogen receptor pathway is directly related to insulin sensitivity, type I diabetes, and the EMT process." (PMID 24466155, 2014). "New therapeutic approaches consist of use of etanercept for reducing insulin dose in type 1 diabetes, probiotics in atopic eczema, and melatonin in viral infections." (PMID 25015124, 2014). "This increased insulin requirement can induce an earlier presentation of type 1 diabetes and/or an increasing incidence by enlarging the proportion of susceptible children progressing to overt disease." (PMID 24498320, 2014). "Type 1 Diabetes (T1D) is a multifactorial autoimmune disease in which the insulin-secreting beta (β) cells within the pancreatic islets are destroyed." (PMID 24466007, 2014). "Type 1 diabetes (T1D), the immune mediated form of diabetes, is a relatively common disorder that results from the destruction of insulin-producing -cells of the pancreas." (PMID 24705439, 2014). "A single drug treats type-1 diabetes in mice by dampening inflammation and enhancing insulin production." (PMID 25549298, 2014). "The onset of metabolic dysregulation in type 1 diabetes (T1D) occurs after autoimmune destruction of the majority of pancreatic insulin-producing beta cells." (PMID 24722187, 2014). "The prescribing prevalence of insulin dependent and non-insulin dependent diabetes was examined across regions." (PMID 25335968, 2014). "Type I diabetes is characterized by autoimmune destruction of islets and requires lifelong administration of insulin to maintain normoglycemeia." (PMID 24204883, 2013). "In Type 1 diabetes, the insulin-producing β-cells within the pancreatic islets of Langerhans are destroyed." (PMID 25408874, 2013). "Type 1 diabetes (T1D), also known as juvenile diabetes, is an autoimmune disease characterized by the destruction of insulin-producing β-cells within the pancreatic islets of Langerhans." (PMID 25408874, 2013). "In Type 1 diabetes, related mechanisms are thought to generate peptides from the insulin B chain, which when presented on MHC-II are specifically recognised by diabetogenic Type B T cells, leading to disease." (PMID 23319341, 2013). "To date, the replacement of ß-cells by pancreas and pancreatic islet transplantation are the only concrete alternatives for re-establishing the endogenous insulin secretion in patients with type 1 diabetes." (PMID 23424628, 2013). "To clarify these issues, we screened a random peptide library with sera obtained from 58 patients with recent onset type 1 diabetes, before insulin therapy." (PMID 23469060, 2013). "Participants who reported using insulin products AND who reported diagnosis before age 31 (n = 559) or did not provide an age of diagnosis (n = 62) were categorised as type 1 diabetes." (PMID 24245780, 2013). "Type 1 diabetes is an autoimmune disease that results in destruction of the insulin-producing beta-cells." (PMID 23613946, 2013). "There is some evidence that suggests improvement in metabolic control of poorly controlled adolescents with type 1 diabetes when metformin is added to insulin therapy." (PMID 23415113, 2013). "In this prospective observational study, 17 patients with type 1 diabetes underwent a standardized insulin infusion test." (PMID 24023652, 2013). "The higher proportion of younger patients in the rapid-acting insulin analogue group suggests the possibility of a higher prevalence of patients with type 1 diabetes." (PMID 24244557, 2013). "Type 1 diabetes (T1D) is an autoimmune disorder, in which insulin-producing beta cells are destroyed by the cellular immune system." (PMID 23977133, 2013). "The increase in the numbers of diabetic people concerns both insulin and non-insulin dependent diabetes." (PMID 23837500, 2013). "A total of 34 pediatric type-1-diabetes patients were observed for 7 months, divided into 2 groups – on pumps and on insulin analogue therapy." (PMID 24079842, 2013).
type 1 diabetes (continued). "The aim of the current study was to establish the efficacy and safety of insulin detemir in children aged 2–16 years with Type 1 diabetes over 52 weeks of treatment." (PMID 23094597, 2013). "A study demonstrated that the initiation of CGMS before subcutaneous insulin infusion increases the CGMS frequency use in type 1 diabetes mellitus patients and significantly reduces the time spent in hypoglycemia." (PMID 26824930, 2013). "Insulin therapy delivered via multiple daily injections (MDI), also known as basal-bolus therapy, or by continuous subcutaneous insulin infusion (CSII) is a mainstay of treatment for type 1 diabetes upon diagnosis." (PMID 27536441, 2013). "Type 1 diabetes (T1D) is a T cell mediated autoimmune disease characterized by immune mediated destruction of the insulin-producing β cells in the islets of Langerhans." (PMID 24367363, 2013). "It has been revealed that the depressed Δ 6 desaturase is restored by insulin stimulation of the gene expression of its mRNA in experimental type-1 diabetes." (PMID 24298385, 2013). "Contemporary insulin regimens allow for flexibility in dietary intake, and dietary intake of youth with type 1 diabetes is similar to that of the general population." (PMID 24195642, 2013). "Continuous subcutaneous insulin infusion (CSII) has been shown to offer significant benefits over treatment involving multiple daily insulin injections (MDI) in patients with type 1 diabetes." (PMID 24223662, 2013). "Type 1 diabetes occurs as a result of the antigen-specific elimination of pancreatic insulin-producing β cells." (PMID 23355840, 2013). "Continuous subcutaneous insulin infusion (CSII) treatment among children with type 1 diabetes is increasing in Sweden." (PMID 24354899, 2013). "In summary, melatonin and insulin plasma levels in type 2 compared to type 1 diabetes are totally different." (PMID 23535335, 2013). "Type 1 diabetes (T1D) is characterized by autoimmune depletion of insulin-producing pancreatic beta cells." (PMID 23437231, 2013). "Results demonstrated that those children who progressed to type 1 diabetes had a dominant IgG1, whereas IgG3 antibodies were more prevalent before the initiation of exogenous insulin therapy." (PMID 24386337, 2013). "Type 1 diabetes (T1D) results from the autoimmune destruction of insulin-producing β-cells in the pancreatic islets of Langerhans." (PMID 23555060, 2013). "The concept of a metabolic memory emerged based on the results of the study, which established that intensified insulin therapy is the standard of treatment of Type 1 diabetes." (PMID 24165454, 2013). "In many children and adolescents, insulin requirements decrease transiently after they have been diagnosed with type 1 diabetes and insulin treatment has been initiated." (PMID 24354899, 2013). "The availability in 1923 of the first insulin preparations for use in humans completely changed the natural history of Type 1 diabetes, enabling physicians to save the life of those patients." (PMID 24348585, 2013). "Continuous subcutaneous insulin infusion (CSII) is considered a therapeutic option for patients with type 1 diabetes inadequately controlled on multiple daily injections (MDI), producing beneficial effects on glucose control and quality of life." (PMID 24170982, 2013). "Type-1 diabetes (T1D) is an autoimmune disease targeting insulin-producing beta cells, resulting in dependence on exogenous insulin." (PMID 24205242, 2013). "Type 1 diabetes (T1D) is an autoimmune disease mediated by T cells that selectively destroy the insulin-producing β cells." (PMID 23671851, 2013). "Type 1 diabetes (T1D) is an autoimmune disease characterized by the destruction of insulin-producing pancreatic beta cells within the islets of Langerhans." (PMID 23922678, 2013). "Defining gene-environment interactions that initiate and/or promote destruction of the insulin-producing beta cells in early life will inform approaches to primary prevention of type 1 diabetes." (PMID 23941366, 2013).
type 1 diabetes (continued). "Another study also demonstrated that the use of Guardian® REAL-Time CGMS led to significantly improved HbA1c values just within three months in type 1 diabetics, despite intensive insulin therapy." (PMID 26824930, 2013). "The objective of this study is to assess the cost of using CSII of insulin to treat children with type-1diabetes in Bulgaria and to compare it with the changes in BMI and HbA1c." (PMID 24079842, 2013). "Type 1 diabetes (T1D) is an autoimmune disease characterized by immune mediated destruction of the insulin-producing β cells in the islets of Langerhans of the pancreas." (PMID 24367363, 2013). "Type 1 diabetes (T1D) is characterized by autoimmune destruction of the insulin-secreting beta cells in the pancreas." (PMID 23360422, 2013). "Diabetes type I is an autoimmune disease that is characterized by selective destruction of insulin-producing β-cells found in the pancreatic islets of Langerhans." (PMID 24279645, 2013). "The objective of this study is to assess the cost of using continuous subcutaneous insulin infusion to treat children with type-1diabetes in Bulgaria, considering changes in body mass index (BMI) and the glycated hemoglobin." (PMID 24079842, 2013). "Note that the study of the hexameric insulin–phenol complex and of the hexamer–monomer conversion are of interest in pharmacology for the treatment of type 1 diabetes." (PMID 23671332, 2013). "In the recent decades, there has been a great deal of interest in developing a closed loop system that embodies an automated insulin delivery system for regulating blood glucose (BG) in type 1 diabetes." (PMID 24260042, 2013). "Type 1 diabetes (T1D) results from the autoimmune destruction of the insulin-producing pancreatic beta cell." (PMID 23483929, 2013). "Type I diabetes (insulin dependent), is distinguishable by selective destruction, via an autoimmune process, of the insulin-secreting β-cell in the pancreatic islets of Langerhans, and pancreatic β-cells are thought to be destroyed by apoptotic death." (PMID 24093976, 2013). "In these focus group interviews, there suggestion that participants who had Type 1 diabetes and, therefore, typically had a longer tenure with insulin use and its titration were slightly less bothered by NSNHEs due to familiarity with them." (PMID 22825805, 2013). "Transplantation of pancreatic islets to Type 1 diabetes patients is hampered by inflammatory reactions at the transplantation site leading to dysfunction and death of insulin producing beta-cells." (PMID 23613946, 2013). "The primary objective is to evaluate the effect of treatment with insulin analogue and human insulin over the preceding 9 months in each treatment arm on the incidence of severe hypoglycaemia in patients with type 1 diabetes prone to hypoglycaemia." (PMID 22727048, 2012). "We measured forearm blood flow and endothelial function in otherwise healthy, pubertal subjects with type 1 diabetes at variable fasting glucose levels, and during euglycemic and hyperglycemic insulin infusion." (PMID 22701470, 2012). "Currently the only real “cure” for type I diabetes is transplantation of the pancreas or isolated islets, which would result in insulin production closer to physiological conditions." (PMID 22675353, 2012). "When in doubt, a patient on insulin should be treated as having type 1 diabetes (whatever the patient’s age)." (PMID 22943220, 2012). "For instance, glucose control with insulin therapy has been shown to increase EPCs while normalization of glucose metabolism by islet transplantation in type 1 diabetes reversed EPC defects." (PMID 22548049, 2012). "The slow recovery of glycogen content in the retina from insulin-treated diabetic rats most likely represent a result of the chronic liver and muscle alterations of glucose disposal reported in type 1 diabetes." (PMID 22363495, 2012).
type 1 diabetes (continued). "Nevertheless, animal models of insulin-dependent diabetes provide a valuable insight into the efficacy of potential adjuncts to insulin therapy in severely hypoinsulinemia states." (PMID 22899950, 2012). "This is the first documented case of allergy to the metacresol component of insulin in the pediatric type 1 diabetes literature." (PMID 22937994, 2012). "The development of type 1 diabetes (T1D) is driven by autoreactive T cells that attack and destroy the insulin-producing β-cells in pancreatic islets, forcing patients to take multiple daily insulin injections." (PMID 22807927, 2012). "Reduction of dietary carbohydrates and corresponding insulin doses stabilizes and lowers mean blood glucose in individuals with type 1 diabetes within days." (PMID 22650646, 2012). "Mean ± SEM exogenous insulin levels in the milk of mothers with type 1 diabetes were 12.22 ± 1.34 mU/L for mother T1-01, 31.54 ± 4.95 mU/L for mother T1-02, and 17.86 ± 4.34 mU/L for mother T1-03." (PMID 22500167, 2012). "Despite technological progress such as self monitoring, use of insulin delivery devices (pens, pumps) the average glycemic control in type 1 diabetes is poor." (PMID 22650646, 2012). "The analysis showed that the overall mean occurrence of hypoglycaemic episodes was lower for short-acting analogues in comparison to regular insulin in patients with type 1 diabetes (−0.2 per patient per month (95% confidence interval: -1.1 to 0.7))." (PMID 22727048, 2012). "Islet transplantation is an attractive alternative treatment to daily insulin injections for patients with type 1 diabetes." (PMID 22666480, 2012). "We now clearly show that in our currently studied adolescent and young adult type 1 diabetes individuals, who, despite being devoid of any characteristics of the metabolic syndrome, are insulin resistant." (PMID 23185996, 2012). "The insulin autoreactivity is particularly pronounced in children with young age at onset of type 1 diabetes." (PMID 22567309, 2012). "Type I diabetes (T1D) is an autoimmune disease characterized by destruction of insulin-producing β-cells in the pancreas." (PMID 23028856, 2012). "While patients with type 1 diabetes will require basal insulin daily, the dose requirement is also expected to fluctuate during recovery." (PMID 23209941, 2012). "Nevertheless, early and intensive insulin treatment in individuals with type 1 diabetes seems to be important to slow cIMT progression independent of other traditional CVD risk factors." (PMID 23185996, 2012). "Attending an educational course on dietary carbohydrate reduction and corresponding insulin reduction in type 1 diabetes gave lasting improvement." (PMID 22650646, 2012). "For example, misregulation of tissue homeostasis plays a central role in Type I diabetes, in which natural populations of insulin-producing -cells are destroyed due to autoimmune defects." (PMID 22829755, 2012). "While type 1 diabetes can be easily managed with regulated insulin administration, repeated administration of insulin prior to every meal is not desirable." (PMID 23320026, 2012). "Artificial recombinant human insulins that are currently used as treatment for patients with type 1 diabetes are typically also only one to three amino acids different in sequence to human insulin." (PMID 22500167, 2012). "The tissue specificity of this sulfatide variant supports a relevance of our findings to the pathogenesis of type 1 diabetes, which is the classic result of selective autoimmune T cell-mediated destruction of insulin-producing β-cells." (PMID 23285123, 2012). "Insulin is a key autoantigen in type 1 diabetes, giving rise to both anti-insulin autoantibodies and T cell autoreactivity in preclinical models and new-onset patients." (PMID 23285123, 2012). "The type 1 diabetes group was insulin resistant, demonstrating a significantly lower GIR compared to the non-diabetic group." (PMID 23185996, 2012).